RIOK1 (RIO kinase 1)
Diseases named in the same sentence as RIOK1 in open-access papers (continued):
Sharing a sentence is not in itself a finding about the gene and the disease.
cancer (22 papers, 2018 to 2025). A tumor composed of atypical neoplastic, often pleomorphic cells that invade other tissues. "Further investigations have shown that abnormal activation of RIOK1 was linked to various biological functions in cancer." (PMID 39865406, 2025). "Combined with earlier studies, these findings suggested that RIOK1 had the potential to be a pan‐cancer biomarker." (PMID 39865406, 2025). "RIO kinase 1 (RIOK1), a protein kinase/ATPase that plays a key role in regulating translation and ribosome assembly, is associated with a variety of malignant tumors." (PMID 39865406, 2025). "The expression of RIOK1 in pan‐cancer was validated by gene expression data of 31 cancer types from the Cancer Genome Atlas (TCGA) project and was generally elevated in cancers." (PMID 39865406, 2025). "The enrichment in the abundance of RIOK1 (ATLANTiC’s portal) is consistent with the data from the Cancer Dependency Map Portal (DepMap), showing higher expression levels of RIOK1 in MSI cell lines compared to MSS." (PMID 37298928, 2023). "Levosimendan shows anti-cancer activity against various cancers by directly inhibiting RIOK1 and RNA processing enzymes." (PMID 38239190, 2023). "RIOK1 overexpression is a characteristic of several malignancies and is correlated with cancer stage, therapy resistance, poor patient survival, and other prognostic factors." (PMID 37301535, 2023). "RIOK1 was found to be essential in 1080 of 1086 tested cancer cell lines, including the PCa cell lines VCaP, LNCaP, DU145, and 22Rv1." (PMID 37301535, 2023). "The expression of RIOK1 in pan-cancer was examined in SangerBox and was generally elevated in cancers." (PMID 35281872, 2022). "RIOK1 represents a new anti-cancer drug target, and the chemical space of its inhibitors has just emerged." (PMID 31206508, 2019). "Differential gene expression profile analysis across 200 cancer cell lines supports that the anti-cancer activity of levosimendan results from its inhibition of RIOK1." (PMID 31206508, 2019). "Pathway analysis implicated RIOK1 in regulating cell cycle and DNA damage response pathways in HCC, but further validation is needed, given that RIOK1 could exert its role in promoting cancer processes through other signaling pathways." (PMID 39865406, 2025). "Researchers believe that the vulnerability of PRMT5 in MTAP‐deficient cancers may extend both upstream of PRMT5 (methionine adenosyltransferase 2A, MAT2A) and downstream of PRMT5 (RIOK1 and other PRMT5 co‐complex members)." (PMID 39711357, 2024). "The results indicated that the expression of RIOK1 was higher in cancer tissues than in normal tissues whether in LUAD or LUSC." (PMID 35281872, 2022). "Importantly, basal cancers express high mRNA levels of genes encoding regulators of ribosome biogenesis such as BYSL, RRS1, RIOK1, POLR1C, and POLR1E (group C)." (PMID 32054925, 2020). "It is reasonable to hypothesize that the inhibition of RIOK1 by levosimendan is directly responsible for its anti-cancer activity." (PMID 31206508, 2019). "Despite our de-validation of MTAP as a biomarker, that predicts cellular sensitivity to RIOK1 inhibition, other molecular alterations of tumor cells might sensitize cancer cells to the inhibition of RIOK1 kinase activity." (PMID 29983885, 2018). "In the context of MTAP-deleted cancers, our study de-validates RIOK1 kinase function as a target." (PMID 29983885, 2018). "To better understand the function of RIOK1 in the HCC, we analyzed the pathway enrichment of DEGs between RIOK1‐high and RIOK1‐low patients in HCC and other cancers using the public database TCGA." (PMID 39865406, 2025).
cancer (continued). "Therapies targeting of MAT2A, RIOK1, or other PRMT5 co‐complex members selectively affect MTAP‐deleted cancers while sparing MTAP‐expressing normal tissues, which address the unmet clinical need of human cancers with the deletion of the MTAP locus." (PMID 39711357, 2024). "Collectively, these findings indicate that knockdown of RIOK1 expression inhibited the migration and invasion of NSCLC cancer cells." (PMID 35281872, 2022). "To investigate the effect of RIOK1 on the chemical resistance of NSCLC cells, we treated cancer cells with cisplatin and performed cell viability analysis to check the survival rate." (PMID 35281872, 2022). "Thus, targeting RIOK1 may provide new opportunities in the cancer treatment." (PMID 31206508, 2019). "Three recent studies have reported an increased dependency of cancer cells harboring a homozygous deletion of the MTAP gene on PRMT5, WDR77 and RIOK1, all members of a PRMT5 containing complex, and the upstream component MAT2A." (PMID 29983885, 2018). "MTAP status alone does not determine the sensitivity to RIOK1 inhibition and our data suggest that the kinase activity of RIOK1 is not a relevant therapeutic target for MTAP-deleted cancers." (PMID 29983885, 2018). "Next, using immunohistochemical, we found that RIOK1 staining in NSCLC tissues mainly located at both nucleus and cytoplasm of the cancer cells, but negative RIOK1 expression was detected in normal lung tissues." (PMID 35281872, 2022). "Our results reveal that the kinase activity of RIOK1 is required for the survival of cancer cell lines irrespective of their MTAP status and cast doubt on the therapeutic exploitability of RIOK1 in the context of MTAP-deleted cancers." (PMID 29983885, 2018). "Coincidentally, a recent study suggested that RIOK1 depletion is not generally toxic to cells but might represent an Achilles heel, specifically for RAS-driven cancers." (PMID 37298928, 2023).
tumor (18 papers, 2013 to 2025). "Researchers also found that RIOK1 can interact with the Ras protein, which often contains mutations that promote tumor growth and metastasis." (PMID 34475988, 2021). "By monitoring tumor volumes, we found that RIOK1 knockdown significantly inhibited tumor growth compared to the control group." (PMID 39865406, 2025). "This was confirmed by another study that showed that RAS-driven tumor cells were dependent on RIOK1 activity of cell proliferation." (PMID 37298928, 2023). "On the other hand, both IRAK1 and RIOK1 were downregulated and involved in tumor initiation, tumor progression, poor outcome, and radiotherapy resistance." (PMID 36845147, 2023). "High RIOK1 expression level positively correlated with pathological grade (p<0.001), tumor size (p=0.049), lymph node metastasis (p=0.01) and survival status (p<0.001) of NSCLC." (PMID 35281872, 2022). "We found that compared with the control group, silencing RIOK1 significantly decreased tumor growth in vivo." (PMID 35281872, 2022). "For colorectal cancer (CRC), several studies have demonstrated a tumor-suppressing effect of SET7/9 through methylation of RIOK1 and SIRT1 or through direct interaction with HDAC6 50,120,124." (PMID 35069908, 2022). "RIOK1 protein expression in tumor cell lines was analyzed by western blot, which showed higher levels in U251 and U87 cell lines compared to A172, U373, and U118 cell lines." (PMID 34475988, 2021). "To confirm that the RIOKs are expressed in GBM, we performed immunohistochemistry (IHC) for RIOK2 on a group of typed tumor specimens (RIOK1 antibodies were unsuitable for IHC)." (PMID 23459592, 2013). "Furthermore, the average tumor mass was significantly greater in the RIOK1 overexpression group compared to the vector group." (PMID 39865406, 2025). "Overexpression of RIOK1 markedly accelerated tumor growth compared to controls." (PMID 39865406, 2025). "Huang et al13 also demonstrated that elevated RIOK1 expression was associated with higher tumor grade and was correlated with absent hormone receptor expression." (PMID 37301535, 2023). "RIOK1 and RIOK2 upregulation was associated with Akt activity in both GBM tumor specimens and cultured cells, and our results show that Akt signaling regulates RIO kinase protein stability, although the exact mechanism by which Akt regulates RIO kinase levels remains undetermined." (PMID 23459592, 2013). "Thus, RIOK1 and RIOK2 overexpression appeared to be correlated with RTK mutation/overexpression and/or PTEN loss in GBM tumor cells." (PMID 23459592, 2013). "Moreover, RIOK1 was found to promote tumor growth as well as malignant cell invasive behavior." (PMID 36845147, 2023). "Functional assays demonstrated that RIOK1 knockdown suppressed HCC cell proliferation, survival, and tumor growth in vivo, while RIOK1 overexpression enhanced these oncogenic phenotypes." (PMID 39865406, 2025). "The functional role of RIOK1 in HCC was analyzed by RTCA assay, clonogenic assay, and flow cytometry in vitro, and by mouse tumor xenograft model in vivo." (PMID 39865406, 2025). "The proliferation of tumor cells was evaluated by MTT assays, the growth curves showed that depletion RIOK1 significantly inhibited A549 and H1299 proliferation." (PMID 35281872, 2022). "The function of RIOK-3 is different from those of RIOK-1 and RIOK-2 in human cells, with RIOK-3 controlling tumor cell invasiveness, suppressing the activity of NF-κB and supporting type I-interferon production." (PMID 25477034, 2014). "A range of GBM cells and cell lines were examined to determine how RIOK1 and RIOK2 expression correlated with tumor cell genotype and phenotype." (PMID 23459592, 2013).
Bacterial infection (1 paper, 2018). "Further study of RIOK-1 may bring new insights into defects in the p38 MAPK pathway underlying human diseases and may reveal new therapeutic opportunities for bacterial infection." (PMID 29719537, 2018). "Bacterial infection activates the p38 MAPK pathway, which transcribes the expression of riok-1 by skn-1, and the activation of riok-1 results in downregulation of the p38 MAPK pathway." (PMID 29719537, 2018).
Cardiovascular disease (1 paper, 2024). "Among these, 10 regions, proximal to or within the genes OVAAL, BMP3, RIOK1, AC096553.5, MCPH1, KCNU1, GLIS3, TUT7, TRIB3, and SYNDIG1, represent novel associations with MI and have not been previously linked to Cardiovascular disease (CVD)-related traits." (PMID 38725839, 2024).
infection (1 paper, 2018). The state of being infected such as from the introduction of a foreign agent such as serum, vaccine, antigenic substance or organism. "RIOK-1 as a negative regulator of immunity against infection conferred resistance to Aeromonas in C. elegans when it was suppressed." (PMID 29719537, 2018). "Here, we discovered that riok-1 is a novel immune suppresser of the infection-activated p38 MAPK pathway in C. elegans and plays an important role in achieving immune homeostasis." (PMID 29719537, 2018). "The expression sites of riok-1 suggest where riok-1 regulates immunity against infection." (PMID 29719537, 2018). "Taken together, A. dhakensis AAK1 infection can induce riok-1 expression in C. elegans." (PMID 29719537, 2018). "In addition, the riok-1 expression level induced by A. dhakensis AAK1 infection in the wild-type N2 worms was significantly higher than those in the pmk-1(km25) mutants, suggesting the coexistence of another pathway that is independent of p38 MAPK-regulated activation of riok-1 expression." (PMID 29719537, 2018). "However, the role of RIOK-1 in innate immunity against infection remains unclear." (PMID 29719537, 2018). "By contrast, suppressed riok-1 expression in the epidermis did not alter the life span of worms with A. dhakensis AAK1 infection." (PMID 29719537, 2018).
prostate (1 paper, 2023). "Taken together, the findings from recent publications and the present study show that the c-myc/E2F transcription factor axis may promote prostate carcinogenesis by multiple mechanisms, including up-regulation of RIOK1." (PMID 37301535, 2023).
RIOK1 also shares sentences with these, for which no sentence is quoted: gastric cancer (2 papers); Anxiety (1); Bcell neoplasms (1); bladder urothelial carcinomas (1); cecal adenocarcinoma (1); cholangiocarcinoma (1); colorectal adenocarcinoma (1); colorectal adenoma (1); Epithelial Ovarian Cancer (1); gastric adenocarcinoma (1); leukemia (1); mesothelioma (1); myeloma (1); ocular melanoma (1); ovarian tumors (1); sarcoma (1).